CXCL6 (C-X-C motif chemokine ligand 6)
Diseases named in the same sentence as CXCL6 in open-access papers (continued):
Sharing a sentence is not in itself a finding about the gene and the disease.
rectal cancer (4 papers, 2011 to 2023). A primary or metastatic malignant neoplasm that affects the rectum. "In this explorative matched case–control study, patients with rectal cancer with anastomotic leakage had significantly elevated preoperative serum levels of the inflammation-related proteins CXCL6 and CCL11, after correction for multiple comparisons." (PMID 35652588, 2022). "Interestingly, rectal cancer patients presenting with AL might have an upregulated inflammatory response preoperatively with increased serum levels of C-X-C motif chemokine 6 (CXCL6) and C-C motif chemokine 11 (CCL11)." (PMID 36975449, 2023). "On the contrary, levels of CXCL6 and CCL11 showed strong correlations with anastomotic leakage in patients with rectal cancer, further supported by the sensitivity analysis." (PMID 35652588, 2022). "As a hypothetical source of the observed differences in circulating CXCL6 and CCL11 levels between rectal cancer cases and controls, immunohistochemical staining of normal tissues from the resection margin displayed no obvious differences between the two groups." (PMID 35652588, 2022).
atherosclerosis (3 papers, 2020 to 2023). A disease characterized by the build-up of fatty material and calcium deposition in the arterial wall resulting in partial or complete occlusion of the arterial lumen. "In the MI-CAD group, concentrations of CCL-8 (on day 7) and CXCL-6 (on day 7) were associated with the progression of atherosclerosis." (PMID 38138896, 2023). "In MI-CAD patients, CCL-8 and CXCL-6 were the key biomarkers associated with atherosclerosis progression." (PMID 38138896, 2023). "In the MINOCA group, factors associated with atherosclerosis progression were concentrations of sVCAM-1 and CCL-21, while in the MI-CAD group, concentrations of CCL-8 and CXCL6 were the main determinants of atherosclerosis progression." (PMID 38138896, 2023). "Based on the signs of the regression coefficients, a direct relationship between the levels of CCL-8 (day 7) and CXCL-6 (day 7) with the progression of atherosclerosis probability was established." (PMID 38138896, 2023). "We found that atherosclerosis progression in MI-CAD patients was related to concentrations of CCL-8 (day 7) and CXCL6 (day 7)." (PMID 38138896, 2023). "In contrast to MINOCA patients, the logistic regression model of the probability of atherosclerosis progression in MI-CAD patients included CCL-8 and CXCL-6, which are pro-inflammatory cytokines that play an important role in atherogenesis." (PMID 38138896, 2023). "We compared the concentrations of pro-inflammatory cytokines and found comparable changes in the content of cytokines CXCL-6, LIGHT, and CCL-8, which may be indicative of similar mechanisms occurring during atherosclerosis in both MI-CAD and MINOCA patients." (PMID 38138896, 2023). "Therefore, elevated levels of CARD8 in atherosclerosis may therefore contribute to increased inflammation in the pathogenesis of atherosclerosis by upregulation of CXCL1, CXCL6, IL-6 and possibly also MCP-1, may aggravate atherosclerosis." (PMID 33154409, 2020).
colitis (3 papers, 2022 to 2025). Inflammation of the colon. "To validate our bioinformatic prediction of CXCL6 upregulation under compound disease conditions, we established a rat model of colitis induced by DSS in combination with PD treatment." (PMID 40936930, 2025). "Collectively, these results suggest that CXCL6 is not only a marker of aggravated colitis under dual stress but may also play a mechanistic role in disease progression." (PMID 40936930, 2025). "After 7 days of induced colitis, upregulation of the expression of 22 genes (Ccl2, Ccl3, Ccl4, Ccl5, Ccl6, Ccl7, Ccl12, Ccl17, Cxcl1, Cxcl2, Cxcl6, Cxcl9, Cxcl11, Ccr1, Ccr2, Ccr3, Ccr5, Ccr8, Cxcr2, Csf3, Osm, and Spp1) was observed in the CβG− group compared to the HβG- control group." (PMID 35163326, 2022). "In a murine model of colitis induced by DSS and PD co-treatment, we observed a significant increase in CXCL6 expression that paralleled exacerbated tissue inflammation and barrier dysfunction." (PMID 40936930, 2025).
fibrosis (3 papers, 2021 to 2025). the formation of excess fibrous connective tissue in an organ or tissue in a reparative or reactive process. "A further correlation analysis revealed that SLIT2 and CXCL6 owned high positive correlation coefficients with fibrosis grade, while the proportion of resting NK cells was negatively correlated." (PMID 35111704, 2021). "CXCL6 had been shown to recruit neutrophils and modulate immune cell trafficking in inflammatory settings, and its neutralization had reduced lung inflammation and fibrosis in experimental models." (PMID 40981201, 2025).
glioblastoma (3 papers, 2017 to 2023). The most malignant astrocytic tumor (WHO grade IV). "There, genes with a higher expression in glioblastoma compared to astrocytoma were VEGFA, 4EBP1, CCL2, PLAU (uPA), CXCL8 (IL8), CXCL10 (IP10), CASP8, HGF, LIF, CD40, CDCp1, TNFRSF11B (OPG), CD274 (PD-L1), IL6, CXCL1, CCL20 (MIP3α), CCL8 (MCP2), CD244, MMP1, TNFRSF9, CXCL6, MMP10, FGF5)." (PMID 35301393, 2022).
myocardial infarction (3 papers, 2018 to 2023). Gross necrosis of the myocardium, as a result of interruption of the blood supply to the area, as in coronary thrombosis. "Further, VEGF-A, IGF-1, HGF, and IL-8 gene expression was promoted at a high level by CXCL-6 in a myocardial infarction model." (PMID 37635970, 2023). "However, changes in CXCL1, MCP-1, and CXCL6 expression may be related to other mechanisms in the process of myocardial infarction, which requires further research effort." (PMID 38124195, 2023).
psoriasis (3 papers, 2015 to 2022). An autoimmune condition characterized by red, well-delineated plaques with silvery scales that are usually on the extensor surfaces and scalp. "In support of the Role of IL-17A in the Psoriasis Pathway, CXCL1, CXCL3, CXCL6, S100A8, S100A9, and CCL20 in the shared signature were all upregulated in both psoriatic skin and colon lesional tissues." (PMID 36396672, 2022). "Based on the IPA analysis BmA pre-exposure before LPS E. coli re-stimulation affected several pathways like granulocyte and agranulocyte adhesion and diapedesis (PPBP/CXCL7, PECAM1, CCL20, CXCL5, CXCL6, MMP9), IL-17 in psoriasis, arthritis and signaling in airway cells (CCL20, CXCL5, CXCL6)." (PMID 30796272, 2019).
Sepsis (3 papers, 2012 to 2022). Sepsis is defined as life-threatening organ dysfunction caused by a dysregulated host response to infection. "We have proceeded to show that stimulation of NOD1 in human endothelial cells induces multiple chemokine and cytokine response genes that are implicated in sepsis including CXCL6, CXCL8, IL1-β and TNFα." (PMID 22870324, 2012). "Our study also found that NM exhibits more powerful neutralization for LPS, TNF-α, and CXCL6, which might partly explain the therapeutic advantage of NM over RM in sepsis treatment." (PMID 35345558, 2022). "In the setting of sepsis, the locally produced chemokines, such as CXCL1, CXCL2, and CXCL6, could lead to neutrophil chemotaxis and subsequent neutrophil infiltration by ligand-receptor binding." (PMID 35345558, 2022). "Subsequent elevation of the genes encoding the inflammatory chemokines such as CCL16, CCL25 and CXCL6, and cytokines such as IL-2, IL-8 and IFNG in concert with delayed activation of the coagulation system are the typical signatures of sepsis." (PMID 27003632, 2016).
small cell lung carcinoma (3 papers, 2006 to 2020). Small cell lung cancer (SCLC) is a highly aggressive malignant neoplasm, accounting for 10-15% of lung cancer cases, characterized byrapid growth, and early metastasis. "Further, CXCL6 acts as an autocrine growth factor in tumor cells itself, i.e., in small cell lung cancer cells expressing its cognate receptors (CXCR1 and CXCR2)." (PMID 31963450, 2020). "Conditions of IL-1β and hypoxia also promotes CXCL6 in cell lines from small cell lung cancer." (PMID 31824496, 2019).
atopic dermatitis (2 papers, 2014 to 2025). "A number of chemokines [CCL2, CCL3, CLL4, CCL8, CCL13, CCL19, chemokine (C-X-C motif) ligand (CXCL) 1, CXCL6, CXCL16] were upregulated in sensitized dogs after allergen challenge, similar to what is observed in human atopic dermatitis." (PMID 25098772, 2014).
breast invasive carcinoma (2 papers, 2023 to 2024). "For the chemokine family genes, CXCL3, CXCL5, and CXCL6, gene expression was positively correlated with dendritic cell infiltration in breast invasive carcinoma-Luminal A patients." (PMID 39201290, 2024). "This was observed for CXCL1 and CXCL6 in breast invasive carcinoma, PPBP in kidney chromophobe, CXCL3 in kidney renal papillary cell carcinoma, CXCL6 in pancreatic adenocarcinoma, CXCL6 in thyroid carcinoma, and CXCL3 in thymoma." (PMID 37686093, 2023). "Additionally, CXCL6 gene expression showed a positive correlation with breast invasive carcinoma Luminal A and Luminal B patients." (PMID 39201290, 2024). "However, in patients with Luminal A breast invasive carcinoma, there was a negative correlation found between ESR1 and CXCL3, CXCL5, and CXCL6 gene expression; and in Her-2 patients, the same relationship was seen between ESR1 and CXCL6." (PMID 39201290, 2024).
depression (2 papers, 2023 to 2025). "CXCL6 and MIP1α/CCL3 add to the growing list of chemokines associated with depression, and a previous meta-analysis supports our finding regarding MIP1α/CCL3 and anhedonia." (PMID 39799156, 2025). "Among their top 10 most significant proteins that were altered after treatment were the same proteins that we found in our OPLS and OPLS-DA models for depression and anxiety (CXCL6, STAMPB, CXCL1, SIRT2, AXIN1, CXCL5, ST1A1, and IL-7)." (PMID 36979692, 2023).
esophageal cancer (2 papers, 2023 to 2024). A primary or metastatic malignant neoplasm involving the esophagus. "Similar correlations were observed in esophageal carcinoma, with CXCL1, CXCL2, CXCL3, and PPBP negatively correlated with EMT, CXCL5 and CXCL6 positively correlated with EMT, and CXCL8 not correlated with EMT." (PMID 37686093, 2023).
pneumonia (2 papers, 2022 to 2024). An acute, acute and chronic, or chronic inflammation focally or diffusely affecting the lung parenchyma, caused by an infection in one or both of the lungs (by bacteria, viruses, fungi, or mycoplasma.). "Pneumonia induced by K. pneumoniae or LPS is associated with the overproduction of IL-1β and neutrophil-related chemokines such as CXCL1, CXCL2, and CXCL6." (PMID 35682923, 2022).
thyroid cancer (2 papers, 2018 to 2023). "Incubation of mast cells with thyroid cancer cell-derived conditioned medium produced a strong upregulation of a set of selected cytokines (TNF-α, CXCL6, and CXCL8), which consistently induced EMT in thyroid cancer cells." (PMID 29977225, 2018).
tongue cancer (2 papers, 2014 to 2020). A malignant neoplasm affecting the tongue. "In line with our data, CXCL6 and CCL7 were previously found to be upregulated in tongue cancer cell-induced LECs, suggesting that these factors represent a common mechanism of lymphatics-induced tumor cell progression." (PMID 31963450, 2020). "The two ligands for CXCR1, CXCL6 and CXCL8, which also activate CXCR2, are both up-regulated, indicating that a shift towards activation of CXCR2 could be of importance for tongue carcinoma." (PMID 24395654, 2014).
viral meningitis (2 papers, 2019 to 2021). Inflammation of the membranes surrounding the brain and spinal cord due to a viral infection. "Like CXCL1, CXCL6 serves as a neutrophil chemoattractant and is elevated in bacterial and viral meningitis." (PMID 34863228, 2021). "Both, bacterial and viral meningitis additionally displayed significantly elevated concentrations of the cytokines CCL1, CCL19, CCL20, CXCL2, CXCL6, IFNγ, and IL16." (PMID 31727097, 2019).
acne (1 paper, 2020). An inflammatory process of the sebaceous glands which is characterized by comedones, nodules, papules and/or pustules on the skin. "CXCL1/keratinocyte-derived chemokine (KC), CXCL2/MIP2 and CXCL5-6/lipopolysaccharide-induced CXC chemokine (LIX) were regarded as functional homologues of IL-8, where CXCL1, CXCL2 and CXCL6 are identified as candidates associated with acne pathogenesis in humans." (PMID 32707723, 2020).
Alzheimer disease (1 paper, 2022). A progressive, neurodegenerative disease characterized by loss of function and death of nerve cells in several areas of the brain leading to loss of cognitive function such as memory and language. "Six of the identified 33 proteins for Alzheimer’s disease in plasma samples corresponded with our findings in serum samples and can now be considered replicated by our study (Casp-8, CXCL5, CXCL6, ST1A1, TRAIL, uPA)." (PMID 36085081, 2022).
bacteremia (1 paper, 2009). "Likewise, neutrophils, important to the amelioration of early bacteremia, are attracted by CXCL6, which was upregulated in the liver (23.1-fold), lung (6.4-17.5-fold), and spleen (14.6-fold) post infection." (PMID 20145715, 2009).
bacterial meningitis (1 paper, 2019). Inflammation of the membranes surrounding the brain and spinal cord due to a bacterial infection. "When comparing cytokine levels between viral and bacterial meningitis, CCL23 and CXCL6 showed the biggest differences between both diseases but differences did not remain significant when applying Bonferroni’s correction." (PMID 31727097, 2019).
breast tumor (1 paper, 2024). "However, IL1R1, ILRAP, IL6ST, CXCL3, CXCL5, and CXCL6 gene expression was higher in normal adjacent tissue than in breast tumor tissue." (PMID 39201290, 2024). "However, IL1R1, ILRAP, IL6ST, CXCL3, CXCL5, and CXCL6 gene expression levels were higher in normal adjacent tissue than in breast tumor tissue indicating that the surrounding non-tumor tissue could also present an inflammation." (PMID 39201290, 2024).
Candidemia (1 paper, 2025). A form of invasive candidiasis where species of CANDIDA are present in the blood. "The highest upregulated expressions in isolated candidemia included CXCL6, LAP-TGF beta-1, CXCL1, CXCL11, and CD5, while in candidemia with bacterial co-infection, CXCL11, CD40, uPA, CXCL1, CXCL10, and IL-18 were the most abundantly upregulated." (PMID 41229429, 2025). "The proteomic profile in candidemia included eight of the most significantly upregulated DEPs: CXCL11, LAP-TGF beta-1, CD40, CXCL1, CXCL6, IL18, CXCL10, and uPA." (PMID 41229429, 2025).
cervical squamous cell carcinoma (1 paper, 2023). A squamous cell carcinoma arising from the cervical epithelium. "In another example, cervical squamous cell carcinoma and endocervical adenocarcinoma exhibited a negative correlation between the expression of CXCL1, CXCL6, and CXCL8 and EMT, whereas the expression of CXCL3, CXCL5, and PPBP positively correlated with EMT." (PMID 37686093, 2023).
cholangiocarcinoma (1 paper, 2025). A carcinoma that arises from the intrahepatic biliary tree (intrahepatic cholangiocarcinoma) or from the junction, or adjacent to the junction, of the right and left hepatic ducts (hilar cholangiocarcinoma). "Here it is discovered that CXCL6 is upregulated in cholangiocarcinoma tissues and promotes proliferation and metastasis of it." (PMID 40305734, 2025). "CXCL6 also mediates immunotherapy resistance through NETs by blocking CD8+T cell infiltration, which may be a potential therapeutic target and biomarker for cholangiocarcinoma." (PMID 40305734, 2025).
chronic hepatitis B (1 paper, 2023). "Interestingly, CXCL6 was one of six genes included in a Cirrhosis Risk Score (CRS), a predictive gene signature for cirrhosis in patients with chronic hepatitis B." (PMID 37296834, 2023).
colon adenocarcinoma (1 paper, 2023). "In colon adenocarcinoma, CXCL1, CXCL2, and CXCL3 negatively correlated with EMT, while CXCL5, CXCL6, PPBP, and CXCL8 positively correlated with EMT." (PMID 37686093, 2023). "For example, in colon adenocarcinoma, the expression of CXCL1, CXCL2, and CXCL3 negatively correlated with EMT, whereas the expression levels of CXCL5, CXCL6, PPBP, and CXCL8 positively correlated with EMT." (PMID 37686093, 2023).
colorectal tumor (1 paper, 2018). "In conclusion, our results showed that the concentration of two angiogenic factors VEGF and CXCL6 is significantly increased in colorectal tumor tissue as compared with that in the adjacent normal tissue; therefore, they might be involved in local angiogenesis and tumor expansion." (PMID 29850390, 2018).
craniopharyngioma (1 paper, 2023). A benign, partly cystic, epithelial tumor of the sellar region, presumably derived from Rathke pouch epithelium. "Regarding adamantinomatous craniopharyngioma, the infiltrating abundance of γδ T cells was positively correlated with CXCL6, while CD8+ T cells were negatively correlated with CXCL6." (PMID 37325556, 2023).
Crohn disease (1 paper, 2016). A gastrointestinal disorder characterized by chronic inflammation involving all layers of the intestinal wall, noncaseating granulomas affecting the intestinal wall and regional lymph nodes, and transmural fibrosis. "Increased numbers of CXCL6 positive mucosal cells have been observed in Crohn's disease biopsies, where, upon activation, upregulation of CXCL6 is more sustained than IL8." (PMID 28018296, 2016).
dementia (1 paper, 2019). Loss of intellectual abilities interfering with an individual's social and occupational functions. "Our study highlights the changes and potential contributions of several chemokines (CXCL1, CCL3, CXCL5, CXCL6, CCL3, CCL19), interleukins (IL8, IL6-RA, IL18-BP), and other immune markers (OSM, ALCAM, OPG, CHIT1, YKL-40, STAMBP, MMP-9, MMP-10) in the prodromal and dementia phases of AD." (PMID 31694701, 2019).
diabetic foot ulcers (1 paper, 2021). "A recent study reported that wound exudate CXCL6 levels were increased in the rapidly healing patients with neuropathic diabetic foot ulcers as a biomarker for wound healing." (PMID 34203413, 2021).
diabetic neuropathy (1 paper, 2024). A chronic, pathological complication associated with diabetes mellitus, where nerve damages are incurred due to diabetic microvascular injury involving small blood vessels that supply these nerves, resulting in peripheral and/or autonomic nerve dysfunction. "Therefore, in treating diabetic neuropathy, CXCL6 appears to hold promise as a new therapeutic target and possible biomarker for JAK/STAT3 activation." (PMID 38882664, 2024).
endocrine cancers (1 paper, 2025). "Notably, endocrine cancers displayed the highest frequency of positive correlations with pro-inflammatory chemokine genes, particularly with CCL8, CCL11, CXCL1, CXCL5, and CXCL6, thus indicating a distinct regulatory pattern in this cancer subtype." (PMID 40806276, 2025).
endometriosis (1 paper, 2021). The growth of functional endometrial tissue in anatomic sites outside the uterine body. "The detection of truncated CXCL6 isoforms is not yet reported in tumors, but downregulation of CD26 and increased levels of CXCL6 coincided in endometriosis, which is often accompanied by abnormal angiogenesis." (PMID 34503058, 2021).
endothelial dysfunction (1 paper, 2022). In vascular diseases, endothelial dysfunction is a systemic pathological state of the endothelium (the inner lining of blood vessels) and can be broadly defined as an imbalance between vasodilating and vasoconstricting substances produced by (or acting on) the endothelium. "Some of the identified proteins do not have a clear role in endothelial inflammation, but we consider OSM, MCP‐2, TGF‐α, and CXCL6 to have an association with endothelial dysfunction when the proteomic results are considered together with our clinical data." (PMID 36467791, 2022). "OSM, MCP‐2, TGF‐α, and CXCL6 are likely to have an association with endothelial dysfunction and some are mostly or additionally involved in IR (MCP‐1, FGF‐21, TRAIL, and ADA) or insulin metabolism (TNFSF14/LIGHT)." (PMID 36467791, 2022).